NEU2 (neuraminidase 2)
Diseases named in the same sentence as NEU2 in open-access papers (continued):
Sharing a sentence is not in itself a finding about the gene and the disease.
tumor (6 papers, 2013 to 2025). "This study identifies tissue-resident tumor-associated neutrophils (Neu2) as a critical driver of CRC progression and immune evasion." (PMID 40959269, 2025). "These tumor cells showed an enhanced association of Neu2 with Atg5 that leads to increased autophagosomes and apoptotic cells." (PMID 33526785, 2021). "Tumor cells isolated from Neu2-plasmid-injected human OC xenograft mice also showed the increased association of Neu2 with Atg5 leading to its desialylation, enhanced autophagosomes, and increased cell death, ultimately leading to a reduction in tumor size." (PMID 33526785, 2021). "Furthermore, this was corroborated by an in vivo study where Neu2 overexpression caused reduction of tumor size and volume in NOD/SCID mice." (PMID 32575925, 2020). "Neu2 overexpression caused a visible reduction in tumor size in NOD/SCID mice model." (PMID 32575925, 2020). "Multiplex immunofluorescence (mIF) staining of clinical CRC specimens further confirmed that CTCF-MIEN1-IL-1β-positive Neu2 cells were enriched in tumor tissues, supporting their tumor-specific role." (PMID 40959269, 2025). "ST analysis of CRLM samples from four patients revealed co-localization of Neu2 and pEMT signatures within metastatic foci areas, implying a tumor-promoting role for Neu2 in metastatic progression." (PMID 40959269, 2025). "Our in vitro observations were further confirmed in the xenograft mouse model where intratumoral injection of Neu2 plasmid reduced the tumor mass." (PMID 33526785, 2021). "We observed a significant increase in the mRNA fold change of NEU2 along with a few pro-apoptotic genes such as CASPASE 3/8, and BAX in Neu2-overexpressed tumor tissue samples as compared to vehicle control." (PMID 32575925, 2020). "There was a marked reduction in tumor volume and weight in Neu2-plasmid injected tumors as compared to the vehicle controls." (PMID 32575925, 2020). "Neu2-overexpressed tumors showed reduction in tumor mass with downregulation of stem cell markers/Shh/mTOR and upregulation of Bax/Caspase8/Caspase3." (PMID 32575925, 2020). "We therefore took an experimental approach to test this idea using the Neu tumor due to its best-defined hierarchical structure from LPs (Neu-1) to AvPs (Neu-2) to AvDs (Neu-3)." (PMID 32840210, 2020). "While N1 marker expression remained stable, Neu2 (differentiation end) exhibited mild up-regulation of N2-associated markers, including ARG1, VEGFA, and CCL2, consistent with an immunosuppressive, tumor-promoting phenotype." (PMID 40959269, 2025). "In contrast, Neu1 and Neu3 were weakly expressed and lacked consistent tumor association, underscoring Neu2 as the dominant infiltrating subset." (PMID 40959269, 2025). "Clinical translation could be accelerated through biomarker-guided cohort stratification in immunotherapy trials, coupled with exploration of small-molecule inhibitors targeting hypoxia-induced CTCF stabilization to disrupt Neu2-mediated tumor progression." (PMID 40959269, 2025). "We next assessed Neu2's pro-tumor effects in CRC cells co-cultured with HL60-derived TANs." (PMID 40959269, 2025). "Neu2-plasmid-injected mice showed reduced tumor size (~4–5-fold) compared to mock." (PMID 33526785, 2021). "Moreover, Neu2-overexpressed tumor tissue samples showed reduction of pluripotent stem cells markers such as OCT4/SOX2/NANOG and PCS specific marker CD133 at the transcript level." (PMID 32575925, 2020). "Furthermore, in vivo model in NOD/SCID mice also confirmed lower mTOR activity, Shh expression, reduced stemness markers and upregulation of apoptotic molecules in Neu2-overexpressed tumor tissue samples." (PMID 32575925, 2020). "Furthermore, Neu2-overexpressed tumor tissue samples showed a lower expression of Shh and mTOR at protein level than vehicle control." (PMID 32575925, 2020).
tumor (continued). "Furthermore, we analyzed the status of several genes linked to apoptosis and stemness properties through qPCR analysis of tumor tissues derived from both vehicle control and Neu2-plasmid-injected groups." (PMID 32575925, 2020). "Neu2, characterized by CTCF-MIEN1-IL-1β signaling, promotes EMT, enhances tumor invasion, and fosters an immunosuppressive TME." (PMID 40959269, 2025). "Neu2 exhibits heterogeneous distribution in CRC, with a predominant localization in hypoxic tumor regions." (PMID 40959269, 2025). "Thus, Neu2 may represent a multifaceted paradigm in tumor biology." (PMID 40959269, 2025). "Together, these data establish that Neu2 promotes CRC invasiveness and tumor growth through CTCF-MIEN1-IL-1β signaling, particularly during pEMT." (PMID 40959269, 2025). "Neu2 may thus reinforce this crosstalk, further sustaining the TME's tumor-supportive functions." (PMID 40959269, 2025).
infectious disease (1 paper, 2025). A disorder directly resulting from the presence and activity of a microbial, viral, or parasitic agent in humans. "In addition, NEU2 is upregulated in fibrotic lesions in human and mouse lungs but its role in infectious disease in the lung has yet to be characterized." (PMID 40822650, 2025).
NEU2 also shares sentences with these, for which no sentence is quoted: ovarian carcinoma (2 papers); amyotrophic lateral sclerosis (1); Anxiety (1); bladder cancer (1); cardiovascular diseases (1); chronic myelogenous leukemia (1); Cognitive impairment (1); fatty liver (1); Huntington disease (1); hyperlipidemia (1); hypertriglyceridemia (1); infection (1); influenza (1); liver disease (1); migraine (1); pulmonary disorders (1); renal fibrosis (1); sarcopenia (1); schizophrenia (1).